CRP (C-reactive protein)
Diseases named in the same sentence as CRP in open-access papers (continued):
Sharing a sentence is not in itself a finding about the gene and the disease.
dilated cardiomyopathy (21 papers, 2011 to 2026). Cardiomyopathy which is characterized by dilation and contractile dysfunction of the left and right ventricles. "This study demonstrates that the inflammatory biomarkers DNI and CRP provide valuable diagnostic and prognostic information in patients with dilated cardiomyopathy." (PMID 41596517, 2026). "C-reactive protein and Delta Neutrophil Index offer complementary diagnostic and prognostic information in dilated cardiomyopathy." (PMID 41596517, 2026). "In this study, we comprehensively evaluated the inflammatory biomarkers Delta Neutrophil Index and CRP levels in patients with dilated cardiomyopathy, both from diagnostic and prognostic perspectives." (PMID 41596517, 2026). "Moreover, in dogs with myxomatous mitral valve disease (MMVD) and dilated cardiomyopathy, plasma CRP concentration was associated with disease severity." (PMID 29573742, 2018). "Both C-reactive protein and Delta Neutrophil Index levels were significantly higher in patients with dilated cardiomyopathy than in controls and were further elevated in those with severely reduced ejection fraction." (PMID 41596517, 2026). "It is noteworthy that CRP and complement deposits have been shown to be frequently present in myocardial biopsy specimen obtained from patients suffering from dilated cardiomyopathy." (PMID 35407379, 2022). "Previous studies have identified that hs-CRP level is an independent prognostic predictor in patients with dilated cardiomyopathy and hypertrophic cardiomyopathies." (PMID 34926619, 2021). "CFR, coronary flow reserve; DCM, dilated cardiomyopathy; BP, blood pressure; CRP, C-reactive protein; LV, left ventricle; BMI, body mass index." (PMID 32599970, 2020). "Diagnostic findings were suggestive of an inflammatory process affecting the myocardium, with elevated cardiac biomarkers, elevated CRP, sinus tachycardia, and dilated cardiomyopathy." (PMID 26413355, 2015). "Although speckle-tracking data were not available in our cohort, integrating inflammatory indices such as DNI and CRP with strain-based echocardiographic markers may offer a more comprehensive and noninvasive approach to phenotyping disease severity and progression in dilated cardiomyopathy." (PMID 41596517, 2026). "Myocardial biopsies from dilated cardiomyopathy (DCM) patients either with or without accompanying chronic myocardial inflammation or virus were immunohistochemically studied for CRP and C5b-9." (PMID 24799767, 2014).
Infertility (21 papers, 2017 to 2025). "Increased serum levels of high-sensitivity CRP (hs-CRP), a more precise CRP assay of inflammation, has also been reported with increased age and BMI, factors that both associate with infertility, and often present in those seeking IVF treatments." (PMID 32215823, 2020). "Therefore, this study aimed to investigate the association of DII and CRP levels in plasma and semen with the quality of semen in infertile men." (PMID 38077946, 2023). "In cardiovascular disease patients, CRP has been shown to be a useful marker of persisting low-grade inflammation and the risk of late complications, and in a previous study in infertile women promising results were seen when combining CAT and seCRP for estimating the risk of TFI." (PMID 31858023, 2019). "This study aimed to investigate the relationship between dietary inflammatory index (DII) and levels of C-reactive protein (CRP) in plasma and semen with the quality of semen in infertile males." (PMID 38077946, 2023). "The high unmet needs for contraceptives were attributed to CRP trends, whilst abstinence, infertility, and high demands for induced abortions were identified to impact the TFR trends significantly." (PMID 37486905, 2023). "The present study investigated the relationship between neoself antibodies and complement components and CRP, indicators of inflammatory status, in infertile patients with impaired implantation." (PMID 37711763, 2023). "The NC in infertile men significantly increased total antioxidant capacity and reduced CRP and TNF-α levels." (PMID 30705687, 2019). "Although moderate inflammation is present in 20-40% of females of reproductive age, assessment of serum CRP levels is not included in routine diagnostic for infertility evaluation so far." (PMID 37361544, 2023). "In addition, biochemical markers of chronic inflammation, such as high concentrations of C reactive protein (CRP), have been prospectively linked to increased infertility." (PMID 37481550, 2023). "Moreover, there were differences between infertility and non-infertility women in the distribution of poverty to income ratio (P = 0.029), marital status (P < 0.001), and C-reactive protein (P = 0.028)." (PMID 37138241, 2023). "The higher CRP levels of our study group could therefore not be explained by these factors associated with infertility." (PMID 37361544, 2023). "It should be emphasized that the causes of infertility in patients with PCOS may be very diverse, including the result of a constantly present disease and chronic inflammation, which is reflected in the results of biomarkers, e.g., proinflammatory cytokines, chemokines and CRP protein." (PMID 40647668, 2025). "Curcumin nanomicelle improved semen parameters and testosterone levels, reduced FSH, LH, and prolactin, and improved oxidative stress through the reduction of serum MDA, CRP, and TNF and by increasing the serum total antioxidant capacity in infertile males." (PMID 34829704, 2021). "In this study, we did not observe a predictive value of cycle day 3 hs-CRP levels on preovulatory follicle development and pregnancy rates among infertile PCOS patients treated with CC." (PMID 28042411, 2017). "In the present study in CAT-positive infertile women, we could not confirm these findings and found that CRP is not a suitable marker for identifying a subgroup at highest risk for TFI." (PMID 31858023, 2019). "In the current study, serum levels of hs-CRP were significantly higher in RPL-PCOS and infertile-PCOS subgroups when compared to the non-PCOS group." (PMID 35700181, 2022).
mastitis (21 papers, 2011 to 2025). Inflammation of breast tissue during lactation or postpartum due to an obstructed duct or infection. "In agreement with our study, an increase of CRP concentration was observed in milk samples from cows with mastitis caused by E. coli." (PMID 32867136, 2020). "Milk CRP concentrations in the cows of our study were similar to previous reports of milk CRP values from cows with mastitis caused by different pathogens." (PMID 32867136, 2020). "The purpose of the study was to determine the immunotherapeutic effect of astaxanthin (AX) on total clinical score (TCS), C-reactive protein (CRP), and neutrophil : lymphocyte ratio in mice mastitis model challenged with pathogenic Staphylococcus aureus." (PMID 26464919, 2014). "Concentration of CRP in milk from mastitis caused by Mycoplasma spp." (PMID 32867136, 2020). "The study reinforces that Hp, AGP, and CRP could be used as tools for diagnosing bovine mastitis caused by different pathogens, as already demonstrated by other authors." (PMID 32867136, 2020). "Previously, although CRP had been identified as a milk APP24 it has not generally been regarded as a bovine APP for use as a biomarker of mastitis, but availability of the immunoassay used here for bovine CRP will allow its diagnostic value to be assessed at a larger scale." (PMID 27412456, 2016). "Milk CRP concentrations were significantly higher (p < 0.05) in samples from cows with E. coli or K. pneumoniae infections; moderate for mastitis caused by Staph. aureus, environmental Streptococcus, and Mycoplasma spp.; and significantly lower (p < 0.05) in mastitis caused by Enterococcus spp." (PMID 32867136, 2020). "Although CRP has been widely studied in conditions like mastitis, recent findings highlight its relevance for assessing broader metabolic disturbances in transition cows, especially when interpreted alongside other metabolic and milk-based indicators." (PMID 41465754, 2025). "The most common investigation ordered for women with mastitis was a diagnostic breast ultrasound in 9% of encounters; other investigations recorded were FBE in 5%, CRP in 2%, and ESR in 1%, breast milk or nipple swab cultures in approximately 2%." (PMID 38730361, 2024). "Blood test results showed that the white blood cell count, percentage of neutrophils, and CRP content in the lactation mastitis group (mastitis) were significantly higher than in the healthy group (healthy)." (PMID 37125159, 2023). "The VIP plots indicate that ferritin and somatic cell count in milk and sera CRP are the strongest discriminators for distinguishing mastitis animals from healthy." (PMID 37504254, 2023). "The sensitivity and specificity of milk parameters for differentiating between mastitis and normal dairy cows was 100% for the ferritin test, while milk CRP showed 93% and 96%, and in the case of Malb, it was 96% and 100%, respectively." (PMID 37504254, 2023). "The sensitivity and specificity of ferritin, CRP, and Malb in serum for differentiating between mastitis and normal cows were 92% and 84%, 98% and 100%, and 95% and 100%, respectively." (PMID 37504254, 2023). "The profile of Hp, AGP, and CRP demonstrated significant correlation, indicating that the three APPs are suggested as biomarkers, in milk, for bovine mastitis." (PMID 32867136, 2020). "Nevertheless, CRP is involved in the local inflammatory response of the udder in cows and was suggested as a valuable parameter of mastitis." (PMID 26209015, 2015). "APPs (ferritin, CRP) in milk and serum have the potential to be used as markers of mastitis." (PMID 37504254, 2023). "Increased pus, large masses, and an elevated CRP level may occur in patients with mastitis infected by C.kroppenstedtii." (PMID 35794560, 2022). "Mastitis caused by Gram-negative bacteria is known for its severe clinical cases that produce tissue damage, which stimulates CRP activation, as previously reported in E. coli infection." (PMID 32867136, 2020).
mastitis (continued). "A 10-folds increase in CRP levels was reported in mastitis cases." (PMID 27956769, 2016). "However, numerous gaps exist in our knowledge of the potential use of Hp, M-SAA3 and CRP assays for detection of mastitis." (PMID 26276568, 2015). "The concentration of CRP was shown to increase in bovine milk during mastitis." (PMID 21430962, 2011). "However, few studies have reported it as a potential marker of mastitic milk, but the availability of limited data on CRP in healthy versus mastitic milk and also its correlation with other biomarkers of mastitis, particularly SCC and other APPs of milk, hinder its use in diagnosis." (PMID 37504254, 2023). "There was a strongly positive significant correlation between milk Hp, AGP, and CRP concentrations from cows with mastitis, which could indicate that pathogens with similar concentration patterns for these APPs induced similar inflammatory responses in the epithelial cells of the udder." (PMID 32867136, 2020). "However, non-lactational mastitis is usually associated with elevated white blood cell count and CRP levels, and shows significant improvement after antibiotic treatment, whereas PB-DLBCL often lacks significant laboratory abnormalities and responds poorly to anti-inflammatory or antibiotic therapy." (PMID 41229502, 2025). "Increases in Hp, SAA, CRP, and AGP release in mammary gland cells have been observed in cases of mastitis, indicating the local production of these APPs in response to bacterial infection." (PMID 32867136, 2020). "Haptoglobin, SAA, and c-reactive protein (CRP) have been identified in milk, indicating their potential as biomarkers of mastitis." (PMID 32867136, 2020). "This can then be used in influencing the diagnosis of mastitis based on the assay of Hp, M-SAA3 or CRP." (PMID 26276568, 2015). "The strong correlations between AGP and Hp (rs = 0.60) and between AGP and CRP (rs = 0.72), indicate that AGP might be a good biomarker for mastitis." (PMID 32867136, 2020). "Moreover, an increase of CRP, LBP, and Lf concentration (approximately 10-, 15-, and 30-fold, respectively) was observed during mastitis in cows." (PMID 30223561, 2018). "While assays for bovine CRP have only recently become available it could be that using such an analyte with a lower detection limit and a large dynamic range will accentuate the value of this APP in detecting mastitis." (PMID 27412456, 2016). "It seems that the CRP does not have the best potential to be used in the detection of mastitis." (PMID 21430962, 2011).
nasopharyngeal carcinoma (21 papers, 2013 to 2026). A carcinoma arising from the nasopharyngeal epithelium. "Another meta-analysis of 5215 patients revealed that elevated serum CRP levels were associated with worse OS and distant metastasis-free survival in nasopharyngeal carcinoma." (PMID 38172843, 2024). "CRP has also been implicated in nasopharyngeal carcinoma (NPC)." (PMID 40565234, 2025). "Recent studies indicate that the novel lymphocyte–C-reactive protein ratio (LCR) is strongly associated with the survival of various tumors, but its prognostic value in nasopharyngeal carcinoma (NPC) is understudied." (PMID 37545573, 2023). "Two Chinese studies indicated that serum CRP level predicted a poor prognosis in patients with nasopharyngeal carcinoma." (PMID 35847918, 2022). "The C-reactive protein-to-albumin ratio is a proven prognostic predictor of nasopharyngeal carcinoma." (PMID 33652976, 2021). "This study aimed to clarify the prognostic utility of high-sensitivity C-reactive protein (hs-CRP) in nasopharyngeal carcinoma (NPC) patients in the Intensity-Modulated Radiotherapy (IMRT) era." (PMID 25874450, 2015). "The utility of CRP on the prognosis of nasopharyngeal carcinoma requires further study." (PMID 39183401, 2024). "C-reactive protein (CRP), which indicates a systemic inflammatory response in cases of carcinoma, has been reported to affect carcinogenesis and tumour progression in cancers such as nasopharyngeal carcinoma." (PMID 30486825, 2018). "In this study, we aim to evaluate the significance of the prognostic nutritional index (PNI) and C-reactive protein/albumin ratio (CRP/Alb) in the prognosis of patients with locally advanced nasopharyngeal carcinoma (NPC)." (PMID 41752776, 2026). "Baseline C-reactive protein (CRP) has been determined as a prognostic factor in nasopharyngeal carcinoma (NPC)." (PMID 30847301, 2019). "The current meta-analysis was conducted to better define the prognostic value of CRP/Alb ratio in patients with nasopharyngeal carcinoma (NPC)." (PMID 30352836, 2018). "Previous investigations have reported that high serum CRP levels predict dismal prognosis in different cancer types, such as breast cancer, diffuse large B-cell lymphoma (DLBCL), nasopharyngeal carcinoma, renal cell carcinoma, and colorectal cancer." (PMID 38172843, 2024). "Although there is no recommended cutoff value for CRP/Albumin ratio, a value of 0.12 found in the current work is consistent with optimal cutoffs of 0.14 and 0.10 reported previously in patients with nasopharyngeal carcinoma and soft tissue sarcoma." (PMID 32181373, 2020). "The C-reactive protein/albumin (CRP/Alb) ratio has been recently identified as a prognostic factor in various cancers, whereas its role remains unclear in metastatic nasopharyngeal carcinoma (NPC)." (PMID 28676731, 2017).
systemic sclerosis (21 papers, 2013 to 2026). A chronic disorder, possibly autoimmune, marked by excessive production of collagen which results in hardening and thickening of body tissues. "In patients with systemic sclerosis, older age and increased levels of c-reactive protein were also factors independently associated with shorter 6MWT distance." (PMID 36333405, 2022). "Associations with some cutaneous features of Ssc were pointed out in this study (telangiectasia) alongside with positive correlations with inflammatory markers (especially CRP)." (PMID 34063287, 2021). "Documented association with systemic sclerosis, recurrent staphylococcal infections with low CRP levels." (PMID 31354706, 2019). "Neutralizing, leads to decreased CRP levels, increased susceptibility to infection.May form stable complexes with IL-6 and contribute to disease progression in systemic sclerosis." (PMID 31354706, 2019). "Elevated levels of C-reactive protein (CRP) in systemic sclerosis (SSc) have been linked to early inflammatory stages of the disease." (PMID 31791379, 2019). "Data on bullous pemphigoid are limited, but CRP can be notably increased, possibly in relapses, whereas evidence regarding CREST syndrome describes elevated CRP values." (PMID 37873776, 2023). "About 25% of patients with systemic sclerosis (SSc) have elevated C-reactive protein (CRP) levels." (PMID 36743676, 2022). "Patient characteristics of all 65 study participants with systemic sclerosis (SSc), presented by CRP status." (PMID 39564499, 2024). "Interestingly, a study trying to reveal such antibodies in some other systemic autoimmune diseases revealed that anti-CRP antibodies were evident in more than half of SLE and in less than half of SCLE patients, whereas Systemic Scleroderma (SS) cases were positive." (PMID 37873776, 2023).
alcoholism (20 papers, 2012 to 2026). "Given the observed potent systemic anti-inflammatory effects of CRP in our alcohol-induced ulcer model, it is plausible that microbial transformation of CRP in the lower gastrointestinal tract contributes to its overall gastroprotective efficacy." (PMID 40647169, 2025). "However, three of them had high leukocyte and platelet count values, and two had high right ventricle systolic pressure and C-reactive protein values and experienced issues related to alcoholism history." (PMID 38201247, 2023). "Additionally, the CRP level was also higher in cannabis, nicotine, and alcohol dependence." (PMID 34712729, 2021). "Plasma leptin concentrations were positively correlated with the plasma IL-6, CRP, and TNF-α levels in the present study, which suggests that the role of leptin as a marker of addiction in alcohol-dependent patients may be related to the changes in inflammatory cytokines." (PMID 32265847, 2020). "Non-responders (DAS28-ESR > 3.2) had a lower frequency of alcoholism (p < 0.04), a higher functional disability score (p < 0.01), and higher ESR, CRP (p < 0.01 and p < 0.05, respectively), and IL-6 levels (p < 0.002) in comparison to responders." (PMID 40362255, 2025).